CD4 (CD4 molecule)
Diseases named in the same sentence as CD4 in open-access papers (continued):
Sharing a sentence is not in itself a finding about the gene and the disease.
Hashimoto thyroiditis (continued). "The mTOR/ACC1/CPT1A fatty acid oxidation pathway of CD4+T cells in Hashimoto’s thyroiditis was increased, and treatment with Etomoxir could inhibit the activation of this pathway, and reverse the reprogramming of abnormal metabolism in CD4+T cells, thereby reducing Hashimoto’s thyroiditis." (PMID 39641893, 2025). "The cell-mediated immune process by CD4+ and CD8+ lymphocyte subsets of T-cells has a major role in the pathogenesis of Hashimoto’s thyroiditis (HT)." (PMID 25506398, 2014). "In an earlier study evaluating the expression of PD-1 and T-cell immunoglobulin and ITIM domain (TIGIT) in normal and diseased tissues we had found the highest TIGIT and PD-1 levels among CD4+ and CD8+ T-lymphocyte located in the germinal centers of Hashimoto thyroiditis." (PMID 34083496, 2021). "In PBMC from Hashimoto's thyroiditis patients, rosiglitazone produced no inhibitory effect on IL-4 expression by CD4+ T lymphocytes." (PMID 23983678, 2013). "In PBMCs from patients with Hashimoto's thyroiditis (HT) and controls, rosiglitazone reduced IFN-γ expression by CD4+ and CD8+ T lymphocytes in a dose-dependent manner, but the degree of inhibition was significantly greater in healthy subjects than patients with HT." (PMID 23983678, 2013).
oral squamous cell carcinoma (32 papers, 2013 to 2025). "A scRNA-sequencing analysis indicated that TDO2+ myofibroblasts distant from the tumor nest induce the transformation of CD4+ T cells into Tregs and cause CD8+ T cell dysfunction in oral squamous cell carcinoma (OSCC)." (PMID 40821701, 2025). "OPMD and oral squamous cell carcinoma (OSCC) tissue sections (N = 270) were analyzed by immunohistochemistry for Treg (CD4, CD25 and FoxP3), Teff (CD8) and immune checkpoint molecules (PD-1 and PD-L1)." (PMID 36009387, 2022). "A study with a small cohort of patients with oral cavity squamous cell carcinoma showed that patients with high CD4 counts had decreased survival." (PMID 30153850, 2018). "For example, CCL18 has been shown to promote the proliferation of oral squamous cell carcinoma cells and recruit naive CD4+ T cells into the tumor microenvironment, leading to their differentiation into regulatory T cells that contribute to tumor immune evasion." (PMID 40433389, 2025). "Consistent with our results, previous studies have reported that a high stromal CD8/CD4 ratio was found to be an independent favourable prognostic factor in oral squamous cell carcinoma, and one study revealed that the CD8/CD4 ratio was higher in cases without metastasis and in low-grade lesions." (PMID 32758195, 2020). "Identification of prognostic genes in the oral squamous cell carcinoma (OSCC) microenvironment revealed that HGF expression significantly correlates with the infiltration levels of B cells, CD4+T cells, CD8+T cells, macrophages, and neutrophils." (PMID 40823073, 2025). "An earlier study indicated that in the patients with Oral Squamous Cell Carcinoma (OSCC), there were abundant CD8+ T-cells around the tumor, and CD4+ T-cells were found to be abundant in most patients, either." (PMID 39341197, 2024). "In early oral squamous cell carcinoma (OSCC), the occurrence of clusters between CD20 B cells and CD4 T cells in the invasive margin (IM) can be captured by using the CD20 cluster score, and is positively associated with patient survival." (PMID 36077836, 2022). "It was reported that RAB19 is negatively correlated with the tumor purity of oral squamous cell carcinoma and positively correlated with the immune infiltration of B cells, CD8 + T cells, CD4 + T cells, macrophages, neutrophils, and dendritic cells." (PMID 34288797, 2021). "The aim of our study was to assess the prognostic character of tumor-infiltrating CD4+, CD8+ and CD56+ cells in oral squamous cell carcinoma." (PMID 34066837, 2021). "We observed a similar requirement for CD4 and CD8 T cells in experiments with Line-1 lung and SCC-VII oral squamous cell carcinoma (manuscripts in preparation)." (PMID 27874054, 2016). "Immunohistochemical method was used to examine the immunoexpression of PD-L1 and number of Foxp3+, CD4+, CD8+ cells in 78 cases of oral squamous cell carcinomas (OSCCs): with better prognosis - OSCCBP (n = 37), and with poorer prognosis - OSCCPP (n = 41), and 18 cases of normal mucosa as a control." (PMID 28669079, 2018). "However, while OPSCC and hypopharyngeal SCC demonstrated better OS in patients with high CD4+ TILs, no significance was observed in laryngeal or oral cavity SCC." (PMID 39123486, 2024). "A study of mice using an OSCC model showed that TEX could suppress tumor immune response by inhibiting proliferation of both CD4+ and CD8+ T cells and reducing infiltration of T cells into tumors, thereby promoting the carcinogenesis of murine oral squamous cell carcinomas." (PMID 31708918, 2019). "However, the dynamics and roles of CD4+ and CD8+ T cells, CD19+ B cells, and CD56+ NK cells in the patients with oral squamous cell carcinoma during treatment remain unclear." (PMID 26587366, 2015). "Immunohistochemical staining for CD4, CD8, FoxP3, CD1a, and p16 was performed in 131 oral squamous cell carcinomas from smokers/drinkers and never-smokers/never-drinkers." (PMID 37345025, 2023).
abortion (31 papers, 2010 to 2025). the ending of pregnancy by removing a fetus or embryo before it can survive outside the uterus. "It was reported that abortion is associated with infiltrations of CD4+ T cells and NK cells and the subsequent production of IFNG in the placenta." (PMID 40872670, 2025). "We wonder if CD4+CD25+ T cells have contributed to the mechanism that the abortion caused by T. gondii is closely dependent on the timing of maternal infection during pregnancy." (PMID 23874852, 2013). "Our previous study demonstrated that CD4+CD25+ T cells were involved in the pathogenesis of abortion caused by T. gondii." (PMID 23874852, 2013). "In TBNK cell group, CD4+ AC was negatively associated with abortion (OR < 1)." (PMID 39388432, 2024). "The abortion caused by T. gondii excreted-secreted antigens at early pregnancy could be partly prevented by adoptively transferring of CD4+CD25+ cells from the mice injected with T. gondii excreted-secreted antigens at late pregnancy, but not from the mice with the same treatment at early pregnancy." (PMID 23874852, 2013). "CD3 on activated & secreting Treg, CD4 on CD28+ CD4+ and CD4 on resting Treg were negatively associated with abortion (OR < 1)." (PMID 39388432, 2024). "In Treg cells, Resting Treg % CD4 Treg, Resting Treg %CD4, CD28-CD127-CD25 ++ CD8br %T cell and CD127 on CD28+ CD45RA+ CD8br were positively associated with abortion (OR > 1)." (PMID 39388432, 2024). "Among the 9 TBNK phenotypes associated with abortion found in our study, the remaining 8 TBNK cell phenotypes were pathogenic to abortion, except for In TBNK cell group, where CD4+ AC had a protective effect on abortion." (PMID 39388432, 2024). "In Maturation stages of T cell group, Naive CD8br %T cell, CD4 on CD45RA+ CD4+ and CCR7 on naive CD4+ were negatively associated with abortion (OR < 1), while CCR7 on naive CD8br was positively associated with abortion (OR > 1)." (PMID 39388432, 2024). "The proportion of CD4+CD25bright T cells in the decidua of women with spontaneous abortion was significantly lower than that in women with induced abortion." (PMID 35414772, 2022). "The adoptive transfer of splenic and thymic CD4+CD25+ cells from CBA/J mice mated with BALB/c males (healthy pregnancy) into abortion-prone mice inhibited the incidence of abortion." (PMID 34298914, 2021). "The data show that ESA or RU486 did indeed attenuate the frequency of CD4+CD25+Foxp3+ T cells in abortion‐prone mice." (PMID 28300338, 2017). "Why CD8+ cells are more abundant than CD4+ in the ovine placenta when abortion due to neosporosis occurs deserves further investigations." (PMID 26739099, 2016). "On day 12 of pregnancy, we found an augmented number of CD4+ Foxp3+ Treg cells in the decidua of abortion-prone females that received hCG-treated BMDCs when compared to females that received mature BMDCs." (PMID 27895621, 2016). "A positive association between several T lymphocyte (CD3, CD4, CD8 and γδ) subsets and occurrence of abortion was also established in the current study." (PMID 24484200, 2014). "Compared to women with induced abortion, patients experiencing spontaneous abortion exhibit fewer decidual and peripheral blood CD4+CD25high T cells recovery." (PMID 22541024, 2012). "In the present study, immunohistochemistry analysis showed that uterine CD4-positive lymphocytes were increased in number with LPS-induced abortion compared to that of normal pregnancy." (PMID 20981318, 2011). "The ratio of CD4+/CD8+ increased significantly (P < .01) in the uterus of LPS-induced abortion mice." (PMID 20981318, 2011). "When Quercetin and Bornyl Acetate were administered in combination to prevent LPS-induced abortion, less CD4+ T cells were counted in the uterine tissue." (PMID 20981318, 2011). "Reduced palmitoylation by 2-bromopalmitate promoted decidual CD4+T (dCD4+T) cell tolerance and decrease the resorption rate of abortion-prone mice, suggesting that elevated palmitoylation level may be associated with RPL." (PMID 40642872, 2025).
abortion (continued). "Excitingly, our research team found that MSCs executed immunotherapeutic effect in both the LPS-induced abortion model and the immune response-mediated spontaneous abortion model via inhibition of CD4+ T cell proliferation and promotion of macrophage M2 polarization." (PMID 33717198, 2021). "Consequently, Foxp3+CD4+CD25+ cells from CD4+CD25−Foxp3− cells by FTY720-induced conversion were adoptively transferred into abortion-prone NOD mice." (PMID 24714634, 2014). "One of them is contributing to Th1 related cytokines encoded genes which proven by the fact that elevated Th1/Th2 cytokine producing CD3(+)/CD4(+) cell ratios were reported in women with a history of recurrent spontaneous abortion (RSA) and multiple implantation failures." (PMID 20920206, 2010). "Thus, IL-17 production by decidual CD4+ T cells does not seem to be associated with spontaneous abortion or unexplained spontaneous abortion, as was reported." (PMID 26798325, 2016). "Conversely, our study also identified negative causal associations in certain T cell maturation stages, including Naive CD8br %T cells, CD4 on CD45RA+ CD4+, and CCR7 on naive CD4+, implying a protective role against abortion." (PMID 39388432, 2024). "PD-1 blockade in vivo was shown to enhance the proliferation of CD4+ and CD8+ T cells in unmated and pregnant mice and to erase the protective effect of Treg cells in Treg treated abortion-prone animals." (PMID 31057559, 2019). "In abortion-prone mouse models, a reduced number of TIM-3+ dNK and CD4+ Th cells can be observed with predominantly Th1 cytokine profiles." (PMID 31057559, 2019). "In those experiencing successful pregnancy and those experiencing unexplained recurrent abortion (URA), the levels of IL-22 produced by decidual CD4+ T cells are higher than those of peripheral blood T cells." (PMID 30669479, 2019). "Apparently, these results demonstrated that the administration of T. gondii ESA did induce diminished capacity of CD4+CD25+ T cells at G5, and then resulted in the abortion." (PMID 23874852, 2013). "In the Quercetin and Bornvl Acetate pretreated mice followed by LPS administration, the ratio of CD4+/CD8+ dropped to 0.562 ± 0.021, lower than that of LPS-abortion group (P < .01)." (PMID 20981318, 2011). "Moreover, there were increased DCreg (CD11bhigh DC) cells and decreased CD4+ and CD8+ T cells detected in the HFD abortion-prone mice relative to those fed the NCD diet." (PMID 34177956, 2021). "We recorded decreased proportions of mature cytotoxic NK cells, CD4+ T cells as well as CD8+ T cells in the decidua, although there was local and systemic augmentation of total NK cells along with uterine DCregs observed in obese abortion-prone mice." (PMID 34177956, 2021). "We also observed fewer dCTLA-4+Tim-3+CD4+T cells and higher expression of Th1-type cytokines, but lower Th2-type and Treg-type cytokines by dCTLA-4+Tim-3+CD4+T cells in female CBA/J mated with male DBA/2 mice, a well-established model of abortion." (PMID 30622243, 2019). "We found that the adoptive transfering of CD4+CD25+ T cells from pregnant mice injected with T. gondii ESA at G5 failed to prevent the abortion." (PMID 23874852, 2013). "To further clarify whether functional regulation of LAG-3 on CD4+T cells is involved in pregnancy maintenance, we first compared LAG-3 expression on dCD4+T cells from mouse model representing normal pregnancy and those prone to abortion." (PMID 41023624, 2025).
myositis (31 papers, 2007 to 2025). "Insl6-deficiency in mice led to a worsened myositis phenotype including increased infiltration of CD4 and CD8 T cells and the elevated expression of inflammatory cytokines." (PMID 25161767, 2014). "The frequency of TIGIT+CD226+ CD4 T cells was positively correlated with the Myositis Disease Activity Assessment (MYOACT) scores (n = 30, r = 0.4239, p = 0.0196)." (PMID 33413573, 2021). "It is also evident that IL-10 sourced from CD4+CD25- effector T cells impair IFN-γ production for the control of acute inflammation and myositis in the diaphragm caused by Trichinella spiralis as well." (PMID 33044969, 2020). "Among these, five genes had a higher expression in CD4+ T cells from HLA-DRB1*03-positive patients with myositis, and eight genes had a higher expression in CD4+ T cells from HLA-DRB1*03-negative patients with myositis." (PMID 30157932, 2018). "Six genes were differentially expressed in CD4+ T cells of HLA-DRB1*03-positive compared with HLA-DRB1*03-negative myositis patients." (PMID 30157932, 2018). "PI4KAP1 was found to have a higher expression in CD4+ T cells of HLA-DRB1*03-positive patients with myositis, and TRGC2, CTSW, HPCAL4, ZNF683, and GOLGA8B were found to have a higher expression in CD4+ T cells of HLA-DRB1*03-negative patients with myositis." (PMID 30157932, 2018). "PD-L1 had a immunoprotective role against myositis in coculture experiments of MHC class I/II labeled myoblasts with CD4+ or CD8+ T cells." (PMID 28716137, 2017). "As shown in the examples and in the summary graph, CD4+CD28null T cells were less sensitive towards glucocorticoid-mediated suppression compared to their CD28+ counterparts in myositis patients (median suppression: 46.8 % versus 68.5 %, n = 6)." (PMID 27039301, 2016). "Deficiency of Insl6 led to an increase in CD4 and CD8 T cell infiltration, increased inflammatory cytokine expression and greater motor function impairment in the myositis model." (PMID 25161767, 2014). "An elevated CD8/CD4 ratio was reported in another patient with nivolumab-related MG/myositis." (PMID 39720481, 2025). "Abatacept therapy has also shown promise myositis; in PM and DM patients treatment resulted in lower disease activity in 8 out of 19 patients and CD4/CD8 T cell ratio in peripheral blood, driven by alterations in CD8+ T cells, correlated positively with muscle endurance improvement." (PMID 36232733, 2022). "STIR‐positive FSHD muscle is characterised by lymphocytic infiltrates, particularly endomysial CD8+ and perivascular CD4+ T lymphocytes, with B cells and macrophages in close proximity to CD4+ T cells at perivascular sites: cellular distributions with similarities to myositis." (PMID 34151531, 2021). "We made a diagnosis of dermatomyositis according to these clinical features, proximal muscle-predominant myogenic change on electromyography, and infiltration of monocytes and CD4+-dominant lymphocytes on skin biopsy, although myositis-associated antibodies were absent." (PMID 24638953, 2014). "In the patients with myositis, CD68-positive macrophages and CD4-positive and/or CD8-positive T cells were observed more frequently than CD20-positive B cells." (PMID 41131373, 2025). "PD1+CD4+ (r = 0.3243, P = 0.0115) and PD1+CD8+ (r = 0.3959, P = 0.0017) T cells were correlated with Myositis Disease Activity Assessment Visual Analogue Scale scores (muscle) in IIM." (PMID 39284778, 2024). "In another patient with nivolumab-related MG/myositis, peripheral blood lymphocyte analysis showed an elevated CD8:CD4 ratio of 1.4, these findings can possibly be related to the activity of nivolumab regardless of induction of MG." (PMID 31753014, 2019). "PM and DM have been modeled as subgroups of myositis in which muscle tissues are infiltrated by T cells, mainly CD8+ T cells in PM and CD4+ T cells in DM." (PMID 30157932, 2018).